HK2 (hexokinase 2)
Diseases named in the same sentence as HK2 in open-access papers (continued):
Sharing a sentence is not in itself a finding about the gene and the disease.
sarcoma (11 papers, 2018 to 2024). A usually aggressive malignant neoplasm of the soft tissue or bone. "To determine if a similar role existed in sarcoma cells, we silenced HK2 in RH30 and U2OS cells using a short hairpin RNA (shRNA) that was confirmed by qRT-PCR and western blotting analysis." (PMID 29696133, 2018). "Collectively, we propose that HK2 represents one of several glycolytic genes regulated by NF-κB that function in the metabolic reprogramming of sarcoma tumors." (PMID 29696133, 2018). "Knockdown of HK2 shifted the metabolic profile in sarcoma cells away from aerobic glycolysis, and re-expression of HK2 rescued the metabolic shift induced by inhibition of NF-κB activity in OS cells." (PMID 29696133, 2018). "Similar to what we observed in sarcoma cells devoid of NF-κB, RH30 and U2OS cells silenced for HK2 also exhibited an increase in ATP-linked mitochondrial oxygen consumption, suggestive of a shift away from the Warburg effect." (PMID 29696133, 2018). "Taken together, these data support the notion that HK2 function in sarcoma cells is dispensable for the proliferation and viability of these cells, but important as a regulator of metabolism." (PMID 29696133, 2018). "In this report, we show evidence suggesting that classical NF-κB promotes the Warburg effect in pediatric sarcomas, and identified HK2 as one of the glycolytic genes directly regulated by classical NF-κB." (PMID 29696133, 2018). "HK2 may be highly expressed in both sarcomas and normal tissue samples, presumably due to the difference in tissue origin of the tissues designated as normal." (PMID 34708035, 2021). "To determine whether HK2 regulation of metabolism in sarcoma cells was dependent on NF-κB, we induced HK2 expression in RH30 and U2OS IκBα SR cells." (PMID 29696133, 2018). "This suggested that NF-κB is a regulator of HK2 in sarcoma cells." (PMID 29696133, 2018). "We next utilized the Seahorse Bioscience XFe24 extracellular flux analyzer to examine whether HK2 depletion affected the metabolic profile of sarcoma cells." (PMID 29696133, 2018). "HK2, GLUT1, PGK1, ENO1 and PKM were found positive correlation with SLC25A37 in sarcoma patients." (PMID 32831652, 2020). "In sarcoma cells, we found that HK2 was not required for cell proliferation or survival, but instead functioned as a regulator of metabolism." (PMID 29696133, 2018).
type 2 diabetes (11 papers, 2009 to 2025). "Thus, loss of adipose HK2 causes selective insulin resistance and thereby contributes to the pathogenesis of type 2 diabetes." (PMID 36920797, 2023). "Moreover, IRS2 and HK2 were associated with type II diabetes mellitus." (PMID 37958518, 2023). "HK2 is enriched in IL-17 signaling pathway, type II diabetes mellitus, terpenoid backbone biosynthesis, systemic lupus erythematosus, and tyrosine metabolism." (PMID 39044840, 2024). "The treatment of type 2 diabetes involves metformin binding to the HK2 and G-6-P sites, resulting in the dissociation of HK2 from mitochondria and facilitating cellular apoptosis." (PMID 38720279, 2024). "From those genes, we manifested that the expression of three critical genes in the type II diabetes pathway was altered, including HK2 (down-regulated), PRKCZ (up-regulated) and SOCS3 (down-regulated)." (PMID 35606885, 2022). "For the significantly decreased activation and expression of HK2 in type II diabetes, it was investigated as a promising candidate gene for type II diabetes." (PMID 26862397, 2016). "This can explain the decrease in expression of HK2 in the type 2 diabetics since subjects were submitted to a hyperinsulinemic clamp before samples were taken." (PMID 19668377, 2009). "Elucidating the molecular mechanism of HFD-induced translational repression of HK2 may lead to a novel strategy in the treatment of insulin insensitivity and type 2 diabetes." (PMID 36920797, 2023). "Roxadustat exposure led to induction of HIF target gene mRNAs for GLUT1, HK2 (encoding hexokinase 2), MCT4 (encoding monocarboxylate transporter 4) and HIF-P4H-2 (also known as PHD2 or EGLN1) in myotubes from donors with NGT, with a blunted response in myotubes from donors with type 2 diabetes." (PMID 38814443, 2024). "Exposure to roxadustat led to an increased mRNA expression of HIF target genes GLUT1, HK2, MCT4 and HIF-P4H-2 in myotubes from donors with NGT whereas this response was blunted in myotubes from donors with type 2 diabetes." (PMID 38814443, 2024). "Treatment with roxadustat led to induction of HIF target gene mRNAs for GLUT1 (also known as SLC2A1), HK2, MCT4 (also known as SLC16A4) and HIF-P4H-2 (also known as PHD2 or EGLN1) in myotubes from donors with NGT, with a blunted response in myotubes from donors with type 2 diabetes." (PMID 38814443, 2024). "Furthermore, it has been shown that HK2 expression is stimulated by insulin in healthy individuals but not in obese or type 2 diabetes patients." (PMID 19668377, 2009).
preeclampsia (10 papers, 2014 to 2025). Preeclampsia is a hypertensive disorder of pregnancy that is characterized by new-onset hypertension with proteinuria presenting after 20 weeks of gestation, and depending on mild or severe forms may initially present with severe headache, visual disturbances, and hyperreflexia. "In preeclampsia, that is a pregnancy disorder characterized by high maternal blood pressure, downregulation the endometrial HK2 was associated with defective decidualization and considered as a potential contributor to preeclampsia." (PMID 36574146, 2023). "Further analysis of gene regulatory networks, including transcription factor–gene, gene–microRNA, and drug–gene interactions, revealed that seven hub genes (HK2, SRSF10, SOD1, ERO1L, IRF3, MME, and SH3BP5) were strongly associated with preeclampsia." (PMID 40966654, 2025). "Constructed a protein–protein interaction (PPI) network, identifying 10 hub genes, seven of which (HK2, SRSF10, SOD1, ERO1L, IRF3, MME, and SH3BP5) were strongly linked to preeclampsia." (PMID 40966654, 2025). "There have been confounding results in the field as to the direction of altered HK2 expression in preeclampsia, with most findings observed in decidual tissue." (PMID 39028417, 2024). "A recent study linked preeclampsia with decreased expression of the RNA-binding protein SORBS2, which promotes glycolysis, cell proliferation, and migration of HTR-8/SVneo cells by increasing the stability of the HK2 enzyme (Song L 2024)." (PMID 40251569, 2025). "PKM, LEP, and HK2 could be promising biomarkers for preeclampsia, which might regulate the pathogenesis of preeclampsia via metabolism pathways and immune microenvironment." (PMID 38166707, 2024). "In summary, this research has identified PKM, LEP, and HK2 to be promising biomarkers for preeclampsia, which might regulate the pathogenesis of preeclampsia via targeting autophagy, metabolism and immune microenvironment." (PMID 38166707, 2024). "Downregulation of endometrial glycolytic genes such as HK2 has also been observed in preeclampsia." (PMID 36574146, 2023). "For example, the HK2P1 pseudogene may contribute to preeclampsia by acting as a competing endogenous RNA for hexokinase 2 and impairing decidualization." (PMID 35629146, 2022). "HK2, PLOD2, and TREM1 may be associated with the development of pre-eclampsia, and their mechanisms of action in preeclampsia need to be further investigated." (PMID 36541903, 2022). "Molecular docking analysis showed that HK2, SH3BP5, and SOD1 exhibited significant binding affinities with two preeclampsia drugs." (PMID 40966654, 2025). "This study demonstrated that placental HK2 is elevated in both FGR and preeclampsia, with elevated expression in trophoblasts that have likely undergone a cell fate commitment." (PMID 39028417, 2024). "Then, immune microenvironment analysis turned out that M2 macrophages were reduced in preeclampsia women (p<0.0001) and were negatively correlated with the expression of PKM (r=-0.2, p<0.05), LEP (r=-0.4, p<0.0001), and HK2 (r=-0.3, p<0.001)." (PMID 38166707, 2024). "Placental mRNA expression was examined for the 8 genes enriched in isolated trophoblast side-population cells (CXLC8/IL8, ELL2, GATA6, HK2, HLA-DPB1, INTS6, SERPINE3, UPP1) in placentas obtained from participants with early onset preeclampsia (n = 78) or fetal growth restriction (n = 30)." (PMID 39028417, 2024). "Increased HK2 was observed in all diseased groups but was most pronounced in placentas obtained from pregnancies complicated by preeclampsia (FGR p = 0.015, FGR/preeclampsia p = < 0.0001, preeclampsia p < 0.0001)." (PMID 39028417, 2024). "Interestingly, HK2, PLOD2, and TREM1 were significantly upregulated in the early-onset preeclampsia cohort, and TREM1 was also significantly upregulated in PE patients with concomitant hemolysis, elevated liver enzymes and low platelets (HELLP) complications." (PMID 36541903, 2022).
preeclampsia (continued). "Interestingly and in accordance with the role of hypoxia in preeclampsia, HIF1A can regulate the expression of several top DEGs identified in the meta-analysis including: LEP, FLT1, INHA, BHLHE40, SPAG4, HK2, HILPDA and ERO1L." (PMID 27802351, 2016).
rheumatoid arthritis (10 papers, 2021 to 2025). A chronic, systemic autoimmune disorder characterized by inflammation in the synovial membranes and articular surfaces. "Increased expression of hexokinase 2 (HK2), a key enzyme of glucose metabolism, results in an invasive and migratory cellular state in rheumatoid arthritis associated FLS." (PMID 34831065, 2021). "The effect of glucose metabolism on rheumatoid arthritis is mainly reflected in the enhanced cell migration and invasion ability caused by high HK2 expression and the increased extracellular lactic acid level." (PMID 34521930, 2021). "In rheumatoid arthritis, HK2 promotes fibroblast-like synoviocyte activation and synovial hypertrophy, contributing to disease progression." (PMID 40643524, 2025). "Glucose metabolism, specifically, hexokinase 2 (HK2), has a critical role in rheumatoid arthritis (RA) fibroblast-like synoviocyte (FLS) phenotype." (PMID 37529037, 2023). "Receiver-operating characteristic analysis of Hexokinase 2 (HK2) in peripheral blood mononuclear cells from patients with Rheumatoid arthritis (RA) and Osteoarthritis (OA)." (PMID 34160468, 2021). "The aim of this study was to evaluate the potential of circulating hexokinase-2 (HK2) in peripheral blood mononuclear cells (PBMCs) of rheumatoid arthritis (RA) patients." (PMID 34160468, 2021). "Univariate logistic regression analyses showing the disease phenotypes of Rheumatoid arthritis (RA) in correlation to Hexokinase 2 (HK2) status as dependent variable." (PMID 34160468, 2021). "Correlation coefficients between Hexokinase 2 (HK2) levels and clinical parameters in rheumatoid arthritis patients (n = 65)." (PMID 34160468, 2021).
acute myeloid leukemia (9 papers, 2020 to 2025). Acute myeloid leukemia (AML) is a group of neoplasms arising from precursor cells committed to the myeloid cell-line differentiation. "Likewise, miR-185 can induce apoptosis and quench glycolysis in acute myeloid leukemia via the down-regulation of glucose uptake, lactic acid secretion and HK2 expression." (PMID 34659523, 2021). "In acute myeloid leukemia (AML), nuclear HK2 interacts with chromatin-regulating proteins to enhance chromatin accessibility at loci associated with leukemic stem cell signatures and DNA repair pathways." (PMID 40868343, 2025). "Overexpressed HK2 has been found to promote, upon its nuclear localization, a stem cell phenotype in both acute myeloid leukemia (AML) and normal hematopoietic cells." (PMID 37190033, 2023). "Similar properties of HK2 have been shown in a model of acute myeloid leukemia (AML)." (PMID 37834214, 2023). "While HK1 and HK2 are ubiquitously expressed, the less well-studied HK3 is primarily expressed in hematopoietic cells and tissues and is highly upregulated during terminal differentiation of some acute myeloid leukemia (AML) cell line models." (PMID 35538058, 2022).
Cirrhosis (9 papers, 2016 to 2025). A chronic disorder of the liver in which liver tissue becomes scarred and is partially replaced by regenerative nodules and fibrotic tissue resulting in loss of liver function. "IHC analysis revealed significantly greater HK2 positivity in liver sections from patients with cirrhosis than in those from NCs." (PMID 41208891, 2025). "While GCK, but not HK2, is expressed in normal hepatocytes, the expression of HK2 occurs during cirrhosis and increases as the disease progresses to carcinoma." (PMID 33594203, 2021). "Consistent with this, we found that HK2 is not only highly expressed in HCC but also in cirrhosis as compared to normal liver samples, suggesting the occurrence of the glycolytic phenotype early in the hepatocarcinogenetic process." (PMID 30430110, 2018). "We also evaluated HK2 expression in liver samples from patients with cirrhosis and NCs." (PMID 41208891, 2025). "Several signaling pathways such as hypoxia inducible factors (HIF), peroxisome proliferator-activated receptors (PPAR) and phosphatidylinositol-4,5-bisphosphate 3-kinase (PI3K) might contribute to HK2 induction in fatty liver disease and its evolution towards cirrhosis and carcinogenesis." (PMID 33594203, 2021). "Detailed histopathological analyses showed significantly higher expression of HK2, as measured by IHC, in dysplasia and HCC than in cirrhosis and normal liver areas (p ≤ 0.05 by Student’s t-test)." (PMID 29386513, 2018). "High mRNA expression of HK2, PFKL, ALDOA, and PKM2 positively correlated with a progression of cirrhosis to HCC and a worse survival rate." (PMID 30430110, 2018). "Recently one study also revealed that the levels of HK2 expression in dysplastic cirrhosis and HCC was higher than that of non dysplastic cirrhosis and normal liver, which indicates that high expression of HK2 is associated with high grade of malignancy." (PMID 27255554, 2016). "However, previous studies have demonstrated that compared with non-dysplastic cirrhosis, the expression level of HK2 is higher in liver cell change/dysplasia in cirrhosis and hepatocellular carcinoma." (PMID 36335239, 2022).
colorectal tumor (9 papers, 2015 to 2025). "We next examined HK2 levels in colorectal tumor and adjacent normal colorectal tissues in 79 CRC patients." (PMID 32564010, 2020). "Furthermore, we compared HK2 expression between 186 primary colorectal tumour tissues and 67 live and lung metastatic CRC tissues from the clinical COAD data of the Gene Expression Omnibus (GEO) data sets (GSE41258)." (PMID 34378321, 2021). "High levels of HK2 expression were observed in the invasive margins of colorectal tumors." (PMID 30967137, 2019).
head and neck cancer (9 papers, 2014 to 2025). A primary or metastatic malignant neoplasm affecting the head and neck. "The Kaplan Meier overall survival analyses (performed on datasets from the TCGA of head and neck cancer patients in UCSC Xena) characterize HK2 expression (both low/high) and associate with significantly poor patient overall survival, thus rendering HK2 as an attractive target." (PMID 38529190, 2024). "Similarly, previous studies have also shown an association of the HK2 gene with advanced tumor grades in cervical and head and neck cancers." (PMID 35328104, 2022). "Further analysis showed that HK2 protein is enriched in stem-like/high-grade sphere cells, and strikingly, HK2 loss resulted in significantly less sphere number in selective medium used to culture head and neck cancer–initiating cells." (PMID 32195170, 2020). "In head and neck cancer cells, triptolide treatment can reduce HK2 protein levels and inhibit the binding of HK2 to mitochondria." (PMID 39991762, 2025). "The link between HK2 expression and MET activation appears to be dependent on the cell line studied, as another group studying MET in head and neck cancer found that HGF treatment only induced HK2 and LDHA expression in one out of the three cell lines tested." (PMID 39062731, 2024). "MiR-143 and miR-138 down-regulated glycolytic enzymes, hexokinase 2 (HK2) and HK1, respectively, in head and neck carcinoma." (PMID 25541689, 2014).
thyroid cancer (9 papers, 2017 to 2025). "SENP1 desumoylated HK2 enhanced glycolysis in thyroid cancer, which promoted thyroid cancer proliferation and metastasis." (PMID 38822351, 2024). "ANP32E contributes to the proliferation and migration of thyroid carcinoma cells by enhancing glycolysis mediated by AKT/mTOR/hk2." (PMID 35280441, 2022). "Importantly, ANP32E stimulates the AKT/mTOR/HK2 signaling pathway to accelerate cell proliferation, migration and glycolysis in thyroid carcinoma." (PMID 38585643, 2024). "Moreover, in different subsets of thyroid carcinoma, upregulation of hexokinase 2 (HK2), that phosphorylates glucose to form glucose 6-phosphate was observed." (PMID 31849832, 2019). "In both [18F]FDG-positive benign nodules and [18F]FDG-positive thyroid carcinomas, the expression of GLUT1, HK2, and MCT4 was increased as compared to [18F]FDG-negative benign nodules." (PMID 36253663, 2023). "[18F]FDG-positive benign thyroid nodules and [18F]FDG-positive thyroid carcinomas with indeterminate cytology showed increased expression of GLUT1, HK2, and MCT4 as compared to the expression in [18F]FDG-negative benign nodules." (PMID 36253663, 2023). "In thyroid cancer, the expression of Anp32e is upregulated and promotes the proliferation and migration of thyroid cancer cells by activating the AKT/mTOR/HK2 signaling pathway." (PMID 36263179, 2022). "The expression of GLUT1 (p = 0.009), HK2 (p = 0.02), MCT4 (p = 0.01), and VEGF (p = 0.007) was statistically significantly different between [18F]FDG-positive benign nodules, [18F]FDG-positive thyroid carcinomas, and [18F]FDG-negative benign nodules." (PMID 36253663, 2023).
cardiac hypertrophy (8 papers, 2020 to 2023). "A previous study on heterozygous HK2-deficient mice revealed that downregulation of HK2 expression in the heart promotes cardiac hypertrophy in response to pressure overload by increasing reactive oxygen species (ROS) production." (PMID 32855642, 2020). "The knockdown of HK2 resulted in exaggerated cardiac hypertrophy via increased reactive oxygen species production." (PMID 37758834, 2023). "Cardiac-specific HK-2 overexpression decreased cardiac hypertrophy in isoproterenol-induced mouse hearts and reduced cardiomyocyte size in neonatal rat ventricular cardiomyocytes." (PMID 34336958, 2021). "In summary, stimulating an increase in HK2 levels and increasing its binding level to mitochondria may be an effective measure to alleviate myocardial hypertrophy.Several findings have been made for the use of HK in the treatment of heart failure." (PMID 37938421, 2023). "In addition, with the accumulation of ROS during cardiac hypertrophy, the level of HK2 in cardiomyocytes decreases and its dislocation from mitochondria increases." (PMID 37938421, 2023). "In addition, HK-2 overexpression reduced ROS accumulation which is upregulated during cardiac hypertrophy." (PMID 34336958, 2021). "Moreover, testosterone supplementation in adult male rats by 5 weeks induced cardiac hypertrophy and upregulated β-mhc, Hk2 and Pfk2 mRNA levels." (PMID 33546773, 2021). "In addition to HK1, the link between HK2 and cardiac hypertrophy is equally important." (PMID 37938421, 2023). "Downregulation of GLUT1, HK2, or GPI completely inhibited YAP-induced cardiac hypertrophy, as indicated by cell size (group 1)." (PMID 35133975, 2022). "Similarly, in the heart, enhanced glucose metabolism through cardiac specific activation of Hexokinase 2 attenuated, rather than enhanced, cardiac hypertrophy by increasing pentose pathway flux, thereby increasing NADPH." (PMID 36809274, 2023).